INS (insulin)
Diseases named in the same sentence as INS in open-access papers (continued):
Sharing a sentence is not in itself a finding about the gene and the disease.
Insulin resistance (continued). "In obesity and insulin resistance, the increased adipocyte mass and the low response to insulin lead to an increased hydrolysis of triacylglycerols, resulting in the enhanced release of free fatty acids to the plasma, which are available for hepatic uptake." (PMID 31035507, 2019). "Our novel study also adds to the very limited evidence on the sex-specific effects of insulin and insulin resistance, by showing a stronger effect for men than women." (PMID 31508506, 2019). "In this animal study, improvement of insulin resistance, indicated by the HOMA-IR index, was associated with decreased serum glucose and enhanced serum insulin levels in the EPA- and capsaicin-treated mice group." (PMID 31022842, 2019). "Muscle insulin resistance thus manifests as lower GLUT-4 expression on the membrane in response to insulin leading to reduced glucose uptake." (PMID 31474943, 2019). "Insulin resistance is defined as the metabolic disordered situation that even higher concentration of insulin is insufficient to control the value of glycemia." (PMID 31407623, 2019). "Glucose (GTT) and insulin tolerance (ITT) tests revealed that MKP-1MKO mice on a HFD produced lower levels of circulating insulin and were insulin sensitive, indicating that they are protected from the development of insulin resistance." (PMID 30401534, 2019). "In our work, for the first time we have elucidated the role of IR expression in DM insulin resistance and we have investigated the effects of acute insulin stimulation on the pathways that regulate skeletal muscle mass in DM1 and DM2 patients." (PMID 30901379, 2019). "Type 2 diabetes mellitus (T2D) as the most common metabolic disorder arises from the impaired function of pancreatic beta cells and/or decreased sensitivity of peripheral tissues to insulin leading to insulin resistance (IR) and hyperglycemia." (PMID 31200723, 2019). "Increased pancreatic secretion of insulin-augmentation of the pancreas and increased insulin sensitivity: Type II DM is characterized by insulin resistance, reduced insulin production, or the failure of pancreatic β-cells." (PMID 31191707, 2019). "Significant small to large correlations were found between higher NEQ total scores and higher HbA1c, insulin resistance, insulin, more breakfast skipping, and feeling full before breakfast." (PMID 31360584, 2019). "For instance, BPA exposed rodents displayed glucose intolerance and global insulin resistance, due to disrupted insulin signaling, via defects in phosphorylation of both the insulin receptor and Akt." (PMID 30881345, 2019). "T1D is insulin-dependent and treated with insulin while T2D results from insulin resistance and is treated with insulin sensitizing agents." (PMID 31382613, 2019). "Adipose tissue actively secretes pro and anti-inflammatory cytokines and plays a major role in the control of the insulin signaling cascade, insulin resistance, and metabolic control." (PMID 31434875, 2019). "A similar analysis for women with high total T showed nonsignificant unadjusted P values for metabolic parameters (BMI, insulin levels, and insulin resistance; P = 0.382, 0.639, and 0.632, resp)." (PMID 30275830, 2018). "Type 2 diabetes is a chronic disease caused by an inherited and/or acquired deficiency in insulin secretion and/or by decreased responsiveness of the organs to secreted insulin (insulin resistance)." (PMID 29659496, 2018). "In order to compensate peripheral insulin resistance, pancreatic β-cells secrete more and more insulin leading progressively to an exhaustion of the pancreas." (PMID 29523782, 2018). "Exendin-4 decreased D-galactose-induced increases in serum glucose and insulin, insulin resistance, lipid profiles, and hepatic enzymes, and improved pancreatic islet insulin secretion and antioxidant defense status." (PMID 29321828, 2018). "In the early stage of insulin resistance, blood-glucose increases and stimulates insulin secretion by islet beta cells." (PMID 30692925, 2018).
Insulin resistance (continued). "As phosphorylation at tyrosine residues is essential for the initiation of intracellular signaling cascade and normal insulin action, TNFα leads to insulin resistance." (PMID 29576769, 2018). "There are reports linking ROS to induction of insulin resistance, impairment of insulin synthesis and β-cell insulin secretion." (PMID 30563087, 2018). "It was also found that serum progranulin contributes to developing insulin resistance through increasing IL-6, which in turn, impairs insulin signaling by stimulating SOCS3 expression." (PMID 30096951, 2018). "First, adipose tissue insulin resistance is found in mice and humans that display whole body insulin resistance and insulin resistance at this site can influence whole body insulin sensitivity." (PMID 29402381, 2018). "Our results demonstrated that the extent of increases in some metabolic variables (body weight, insulin resistance, AUCg, and insulin) actively influences the TCF7L2 expression in the liver, skeletal muscle, and adipose tissues." (PMID 29713286, 2018). "Insulin resistance interferes with insulin-induced glucose uptake by muscle and other insulin-dependent tissues." (PMID 30307959, 2018). "The HOMA-IR derives from measurements of fasting plasma glucose and insulin concentrations primarily reflecting hepatic insulin resistance." (PMID 30400254, 2018). "Excessive accumulation of reactive oxygen species (ROS) has been shown to disrupt the insulin signaling pathway, thereby contributing to insulin resistance (IR)." (PMID 29316632, 2018). "Insulin resistance refers to a condition in which insulin-responsive cells undergo a less than normal response to insulin, such as a reduced activation of endothelial nitric oxide synthase in endothelial cells." (PMID 30116482, 2018). "Fasting serum glucose, insulin, lipid profile and homeostatic model assessments of insulin resistance (HOMA-IR) were measured to evaluate the metabolic parameters." (PMID 29789273, 2018). "As a result of insulin resistance, the pancreas attempts to compensate by secreting increasing amounts of insulin, resulting in hyperinsulinemia." (PMID 30170598, 2018). "While acylated ghrelin has been shown to exert hyperglycemic effects leading to insulin resistance, the unacylated ghrelin counters hyperglycemia and enhances insulin sensitivity." (PMID 29487749, 2018). "How do circulating monocytes contribute to insulin resistance in peripheral (insulin-sensitive) tissues?" (PMID 29649324, 2018). "Within-group comparisons also showed a favorable effect of probiotics intake on glucose, insulin, C-peptide level, and insulin resistance." (PMID 29914095, 2018). "It is known that peripheral insulin resistance and impaired insulin secretion are two of the major pathological changes associated with T2DM." (PMID 29682407, 2018). "Large amounts of studies have shown that TZDs improve insulin sensitivity in various animal models with insulin resistance and patients with type 2 diabetes." (PMID 30225267, 2018). "Hepatic CB1R-induced ER stress contributes to insulin resistance by inhibiting insulin signaling via several ER stress-dependent mechanisms." (PMID 29570673, 2018). "Prolonged overnutrition and low levels of physical activity result in adipose tissue dysfunction, characterised by adipocyte hypertrophy, macrophage infiltration, impaired insulin signalling and insulin resistance." (PMID 29478099, 2018). "Tissue and blood samples were collected to determine the effects of the treatments on visceral fat pad mass, fasting plasma levels of cholesterol, insulin, glucose, triglycerides, insulin resistance (HOMA-IR) and glucose tolerance." (PMID 30479649, 2018). "The ensuing insulin resistance puts a strain on pancreatic β-cells, which keep secreting excessive amounts of insulin in order to maintain normal glucose homeostasis." (PMID 29495350, 2018).
Insulin resistance (continued). "The current study indicates that only insulin resistance has a significant effect on the relationship between structural changes in key brain regions sensitive to insulin and cognitive deterioration." (PMID 30400348, 2018). "Other findings suggest that the CCL2-CCR2 signaling pathway disruption reduces adipose tissue macrophage content ameliorating insulin resistance and improves insulin sensitivity." (PMID 29507865, 2018). "One of the possible explanations is that in nonobese individuals high levels of proinflammatory cytokines found in severe forms of psoriasis are responsible for development of insulin resistance through modification of the insulin signaling pathway." (PMID 30011841, 2018). "One of the criteria for type 2 diabetes, is insulin resistance in different body tissues such as skeletal muscle, liver and fat tissues that occurs due to impaired peripheral receptor signaling of insulin." (PMID 30276146, 2018). "Recent studies have shown that abnormalities in the membrane content of GLUT4 lead to impaired insulin sensitivity and, thereby, to insulin resistance or type 2 diabetes." (PMID 29385746, 2018). "Although the magnitude of insulin resistance induced by prolonged fasting in lean participants was similar to overnight fasted participants with modest obesity, the metabolic signatures and insulin signaling data reveal distinct differences." (PMID 30183740, 2018). "The manifestation of MetSyn has been attributed to insulin resistance; as such, for this review, we will focus on insulin signaling and insulin resistance (used interchangeably with low insulin sensitivity) as it pertains to MetSyn." (PMID 29462993, 2018). "Nevertheless, blunt of SIRT3 and SIRT1 in C2C12 cells impairs insulin pathway and stimulates insulin resistance." (PMID 30559718, 2018). "Both male and female IF groups exhibited significant increases in fasting glucose and plasma insulin and glucose tolerance and insulin resistance at either 10- or 12-weeks." (PMID 29534545, 2018). "The assumption of hepatic insulin resistance in HS/HS rats was further supported by the calculation of TyG Index, a surrogate method to assess insulin sensitivity." (PMID 30061916, 2018). "GDM is characterized by the impairment of first-phase insulin secretion function and insulin resistance." (PMID 29541163, 2018). "In response to hyperglycemia and insulin resistance, insulin secretion is increased by pancreatic beta cells to maintain normal glucose homeostasis leads to hyperinsulinemia in the initial stage of type 2 diabetes." (PMID 30072892, 2018). "Intrauterine BPA-exposed animals to 5 μg/kg/day displayed higher plasma insulin levels, and those treated with the doses of 5 and 5,000 μg/kg/day showed insulin resistance." (PMID 30429829, 2018). "A significant decrease in the concentration of alanine aminotransferase (p<0.01) and asparagine aminotransferase (p<0.01) was observed, along with a decrease in the amount of insulin (p<0.05) and insulin resistance (p<0.05)." (PMID 30631760, 2018). "In general, postprandial hyperglycemia is strongly affected by skeletal muscle insulin resistance and defects in pancreatic insulin secretion, whereas fasting hyperglycemia is affected by hepatic insulin resistance." (PMID 30425271, 2018). "We performed intracerebroventricular insulin injection and hyperinsulinaemic–euglycaemic clamp studies to examine the effect of this early nutritional manipulation on central and peripheral insulin resistance." (PMID 30043179, 2018). "Insulin resistance (IR) is a condition of decreased sensitivity or responsiveness of insulin-sensitive tissues to insulin." (PMID 29755474, 2018). "In this study, our patients had higher insulin and insulin resistance defined by HOMA-IR connected to higher ox-LDL than the healthy control group." (PMID 29933629, 2018).
Insulin resistance (continued). "Serum UA harbored a positive correlation with insulin secretion and insulin resistance indexes in newly diagnosed T2DM patients, which was influenced by age, BMI, and serum lipids." (PMID 29568712, 2018). "A homeostatic model of assessment of insulin resistance (HOMA-IR) supports the finding that higher expression of miR-155 improves insulin sensitivity." (PMID 29770126, 2018). "Insulin signaling downstream AKT pathway in the liver has emerged as critical for the emergence of hepatic insulin resistance." (PMID 30123267, 2018). "Centrally obese individuals have insulin resistance with a compensatory increase in insulin secretion, leading to hyperinsulinemia." (PMID 30072671, 2018). "The role of sphingolipids in insulin sensitivity is relevant since CERs are important elements in insulin resistance and inflammation." (PMID 30474555, 2018). "Insulin resistance is manifested by reducing the ability of insulin to activate the insulin signaling pathway." (PMID 30214428, 2018). "Similar to type 2 diabetes, both impaired insulin secretion and insulin resistance in peripheral tissues and liver are the principal pathogenic components of NODAT." (PMID 29380240, 2018). "Insulin resistance leads to increased release of FFA from adipocytes and the product of fasting plasma FFA by insulin concentration is called adipose tissue insulin resistance." (PMID 30170598, 2018). "This is relevant as several key components of the insulin signaling pathway are known to be inhibited by reactive oxygen specific (ROS), promoting the development of insulin resistance and diabetes." (PMID 30200608, 2018). "Specifically, thiazolidinediones (TZDs), such as rosiglitazone and pioglitazone, are specific PPARγ activators and are used as insulin sensitizers in order to improve insulin resistance in T2DM patients." (PMID 29747466, 2018). "Long‐term consumption of high‐GI foods was proposed to increase insulin demand, promote insulin resistance, impair pancreatic β‐cell function, and eventually lead to type 2 diabetes (Brand‐Miller, 2003)." (PMID 29983953, 2018). "Chronic insulin resistance is also related to diet-induced inflammation, which interrupts insulin's normal function by disrupting the signaling mechanism." (PMID 29721029, 2018). "The purpose of this study was to determine if the inhibitory action of insulin on autophagy remains intact during insulin resistance." (PMID 30047243, 2018). "Fruit and vegetables have been shown to improve insulin sensitivity and insulin secretion to overcome insulin resistance in previous studies." (PMID 29329254, 2018). "T2DM is characterized by increased levels of blood glucose due to impaired insulin sensitivity (insulin resistance)." (PMID 35541310, 2018). "GDM manifests when the increased need for insulin during pregnancy cannot be met, leading to a state of glucose intolerance, insulin resistance and inflammation similar to DM2." (PMID 30558244, 2018). "Insulin resistance in T2D results in impaired insulin-stimulated glucose transport and metabolism in skeletal muscle and adipose, and the defective suppression of hepatic glucose output." (PMID 29316644, 2018). "Insulin resistance entails a greater insulin secretion as a compensatory mechanism before it becomes eventually exhausted due to β cell dysfunction." (PMID 29740397, 2018). "Previous studies have demonstrated that aberrant expression of numerous miRNAs including miR-375 and miR-9 influence insulin signaling pathway, insulin resistance and play a major role in T2D." (PMID 29373500, 2018). "Coexistence of insulin hypersensitivity in peripheral tissues with insulin resistance has been observed before in liver of ob/ob mice and in Cdk4 knockout mice with defects in pancreatic beta cell development and insulin secretion." (PMID 30034366, 2018).
Insulin resistance (continued). "Given these growing links between insulin resistance and mHTT pathology, the disruption of neuronal insulin signaling in mHTT-overexpressing cells unsurprisingly exacerbates mHTT neurotoxicity." (PMID 30149534, 2018). "Rosiglitazone targeted 613 genes, among them, PSMD3 is involved in regulating insulin signaling to mediate insulin resistance." (PMID 30521536, 2018). "CG increased insulin sensitivity as manifested by decreased fasting serum insulin, reduced homeostasis model assessment-estimated insulin resistance (HOMA-IR) and improved oral glucose tolerance." (PMID 30140027, 2018). "On the contrary, the different outcomes of the groups investigated, are likely not caused by the different therapeutics, but rather by the degree of insulin resistance and impaired peripheral insulin sensitivity." (PMID 30564289, 2018). "This disease is characterized by high level of blood glucose due to impaired secretion of insulin and/or insulin resistance." (PMID 29751826, 2018). "Inflammatory mediators also have a causative effect in insulin resistance, with TNF-α being found to increase phosphorylation of insulin receptor substrate-1, which leads to diminished insulin signaling." (PMID 30249283, 2018). "Thequestioning is that hyperglycemia rarely occurs in childhood and, therefore, theevaluation of insulin levels is consensual to diagnose insulin resistance, but datapoint out the need to establish reference curves for a proper assessment." (PMID 30365811, 2018). "HOMA-IR and HOMA-β% are the most common methods of evaluating insulin resistance and insulin secretion in rodent studies and epidemiological studies." (PMID 30428526, 2018). "Regarding to the links among obesity-related insulin resistance, brain mitochondrial dysfunction and dementia, several studies reported that brain mitochondrial dysfunction has been observed in obese-insulin resistant condition with cognitive decline." (PMID 30233495, 2018). "Lf supplementation for 15 weeks significantly reduced serum levels of insulin and glucose, and reduced insulin resistance in HFD-induced obese mice." (PMID 30400147, 2018). "This is likely explained by the compelling evidence that SIRT1 overexpression offers substantial benefits on serum cholesterol and insulin levels and increased resistance to high-fat diet induced glucose intolerance and insulin resistance." (PMID 30131769, 2018). "Accordingly, this study aimed to examine the potential effects of coenzyme Q10, an antioxidant, on insulin resistance and insulin secretion consequent to reduced oxidative stress in individuals with IGT." (PMID 30151373, 2018). "Although human pregnancy induces peripheral insulin resistance, most women display normal glucose tolerance during pregnancy due to increased insulin secretion." (PMID 29896157, 2018). "In the liver, insulin resistance is accompanied by an increased hepatic glucose formation due to an attenuated efficacy of insulin to inhibit hepatic gluconeogenesis and glycogenolysis and to stimulate glycogen synthesis." (PMID 29510489, 2018). "Here the authors show that Snail1 is upregulated by insulin and inhibits lipogenesis by repressing Fasn expression but insulin-mediated Snail1 upregulation is impaired during obesity and insulin resistance." (PMID 30013137, 2018). "Insulin resistance leads to reduced phosphorylation of eNOS in endothelial cells, which attenuates precapillary arteriolar tone reduction and insulin-induced capillary recruitment." (PMID 29718998, 2018). "The impairment of insulin signaling, leading to insulin resistance is a main characteristic of metabolic disorders and type 2 diabetes." (PMID 29592806, 2018). "Both conditions are thought to result from a combination of insulin resistance and inadequate insulin secretion, with GDM generally just emerging at a younger age because of the additional physiological insulin resistance of pregnancy." (PMID 29789944, 2018).